OBSL1 (obscurin like cytoskeletal adaptor 1)
Description:
Core component of the 3M complex, a complex required to regulate microtubule dynamics and genome integrity. It is unclear how the 3M complex regulates microtubules, it could act by controlling the level of a microtubule stabilizer. Acts as a regulator of the Cul7-RING(FBXW8) ubiquitin-protein ligase, playing a critical role in the ubiquitin ligase pathway that regulates Golgi morphogenesis and dendrite patterning in brain. Required to localize CUL7 to the Golgi apparatus in neurons.
Synonyms: KIAA0657
Tractability: PROTAC: ubiquitination databases record sites on it; its protein half-life has been measured.
Gene: Protein-coding gene on chromosome 2 (219,550,727 to 219,571,859, reverse strand). Ensembl gene ENSG00000124006.
Subcellular location: Cytoplasm; Cytoplasm, cytoskeleton, microtubule organizing center, centrosome; Cytoplasm, perinuclear region; Golgi apparatus
Subcellular location (Human Protein Atlas): Centrosome
Pathways (Reactome):
Metabolism of proteins: Neddylation
Gene Ontology:
Molecular function: protein binding; cytoskeletal anchor activity
Biological process: Golgi organization; microtubule cytoskeleton organization; positive regulation of dendrite morphogenesis; protein localization to Golgi apparatus; regulation of mitotic nuclear division; cardiac myofibril assembly; cytoskeleton organization
Cellular component: 3M complex; centrosome; cytoplasm; Golgi apparatus; perinuclear region of cytoplasm; plasma membrane; cytosol; intercalated disc; M band; Z disc
Genetic constraint (gnomAD): Loss-of-function variants: 158 observed, 148.79 expected, observed/expected ratio (o/e) 1.06, 90% interval 0.93 to 1.21. The upper end of that interval is the gene's LOEUF score, 1.21, which puts it in group 5 of 6, group 1 being the genes least tolerant of losing a copy. Missense variants: 2,661 observed, 2,516.8 expected, observed/expected ratio (o/e) 1.06, 90% interval 1.02 to 1.09. Synonymous variants: 1,192 observed, 1,088.3 expected, observed/expected ratio (o/e) 1.1, 90% interval 1.04 to 1.15.
Homologues: Orthologues: chimpanzee OBSL1 (99% identical), macaque OBSL1 (97% identical), rabbit OBSL1 (93% identical), pig OBSL1 (92% identical), rat Obsl1 (89% identical), mouse Obsl1 (84% identical), dog OBSL1 (83% identical), guinea pig OBSL1 (83% identical), tropical clawed frog obsl1 (39% identical), zebrafish obsl1b (38% identical), zebrafish obsl1a (35% identical), Caenorhabditis elegans C34F6.10 (8% identical), and 1 more. Paralogues in human: MYBPC3 (12% identical), MYOM1 (12% identical), MYBPC2 (11% identical), MYOM2 (11% identical), MYBPC1 (11% identical), MYOM3 (11% identical), IGSF22 (10% identical), FNDC3A (8% identical), FNDC3B (8% identical), MYBPH (4% identical), MYBPHL (4% identical).
Diseases named in the same sentence as OBSL1 in open-access papers:
OBSL1 is named in the same sentence as 21 diseases in open-access papers, as found by Europe PMC text mining. Sharing a sentence is not in itself a finding about the gene and the disease. The quoted sentences say what the papers report.
3-M syndrome (21 papers, 2012 to 2025). 3M syndrome is a primordial growth disorder characterized by low birth weight, reduced birth length, severe postnatal growth restriction, a spectrum of minor anomalies (including facial dysmorphism) and normal intelligence. "A recent study demonstrated that a homozygous OBSL1 mutation (c.848delG) can cause Three M Syndrome 2 (3M2), a rare growth disorder characterised by short stature and distinctive facial and skeletal features, in a Pakistani family." (PMID 41300791, 2025). "Lastly, we found a significant allele, rs10932816, in OBSL1, one of the causative genes of Three M Syndrome 2 that has a damaging SIFT prediction." (PMID 38785976, 2024). "Exome sequence analysis showed the presence of a homozygous pathogenic DCLRE1C variant [c.194C > T; p.T65I (NM_001033855)] and a homozygous pathogenic variant in OBSL1, a gene associated with 3M syndrome [c.3922C > T; p.R1308X (NM_001173431)]." (PMID 37520055, 2023). "Compared with the results reported from countries other than China, the proportion of patients with 3M syndrome and mutations of the OBSL1 gene is higher in the Chinese population, while the proportion of those with CDCC8 mutations is lower." (PMID 37719700, 2023). "The OBSL1 variant is related to 3-M syndrome (clinical manifestations include severe intrauterine growth retardation, short stature, recessive spina bifida, compression deformation of long metaphysis)." (PMID 37875969, 2023). "3M syndrome is caused by mutations in three genes (Obscurin-like 1 [OBSL1]; Cullin 7 [CUL7]; Protein 8-containing helix-coiled domain [CCDC8])." (PMID 37520055, 2023). "In conclusion, we identified novel truncating mutations of CUL7 and OBSL1 in Chinese patients with 3M syndrome." (PMID 37719700, 2023). "CUL7 mutations account for 70% of 3M syndrome cases, with the remainder caused by mutations in OBSL1 and CCDC8 occurring in a mutually exclusively manner between these three genes." (PMID 35982156, 2022). "Mutations within the human OBSL1 gene for 3M syndrome-2 typically occur within the first six to eight exons and affect all three human isoforms." (PMID 32933480, 2020). "Of all the positional candidate genes within the identified region, OBSL1 was considered the strongest candidate as mutations in this gene cause 3M syndrome-2 in humans (OMIM 612921)." (PMID 32933480, 2020). "Mutations within OBSL1 have been associated with human 3M syndrome-2, a short stature growth disorder that shows similar clinical signs to BCRHS-affected lambs." (PMID 32933480, 2020). "While cullin-7 mutations are responsible for approximately 77.5% of 3M-syndrome cases, mutations in obscurin-like 1 (Obsl1) and Ccdc8 have also been shown to be associated with the syndrome." (PMID 33114658, 2020). "OBSL1 encoded a cytoskeletal adaptor protein, which was a member of the Unc‐89/obscurin family, and studies showed that 3M Syndrome was associated with this gene." (PMID 28796930, 2017). "The following genetic assessment, through the whole gene sequencing method, revealed a homozygous p.T45Nfs*40 (c.1273 dupA) mutation of OBSL1 gene which led to diagnosis of 3M syndrome." (PMID 27796265, 2017). "CUL7 appears to be the major gene responsible for 77% of 3M syndrome, while OBSL1 mutations account for a relatively small percentage of 16%." (PMID 27796265, 2017). "In our case, on the other hand, we observed that a novel frameshift mutation on OBSL1 caused the 3M syndrome." (PMID 27796265, 2017). "This frameshift variant of OBSL1 has been previously observed in patients with 3-M syndrome and in those studies was detected in cases with a similar ancestry to the family in this study." (PMID 25923536, 2015). "We report here the discovery of a previously known frameshift mutation in OBSL1, providing a diagnosis of 3-M Syndrome 2, which would explain the foetal long bone ultrasound findings." (PMID 25923536, 2015).
3-M syndrome (continued). "Exome sequencing of a premortem blood sample identified the presence of a homozygous DCLRE1C variant [c.194C > T; p.T65I (NM_001033855)] and a novel homozygous pathogenic variant in OBSL1, a gene associated with 3M syndrome [c.3922C > T; p.R1308X (NM_001173431)]." (PMID 37520055, 2023). "Also, CUL7–RBX1 binds OBSL1 and CCDC8 in a complex named ‘3M’ in reference to mutations in the CUL7, OBSL1 or CCDC8 genes causing 3M syndrome." (PMID 35982156, 2022). "In addition, alterations in IGFBP-2 and IGFB5 messenger ribonucleic acid levels were previously documented to be associated with OBSL1 mutations in cases with 3M syndrome diagnoses." (PMID 27796265, 2017). "OBSL1 gene mutations are the underlying causes for approximately 20% of the 3M syndrome patients." (PMID 27796265, 2017). "Biological pathways analysis showed that POLR2B protein could interact with OBSL1 protein, which was associated with one of the commonest primordial growth disorders, 3-M syndrome." (PMID 26884814, 2016). "Since the reported role of CCDC8 mutations in 3-M syndrome links it to Obsl1 and E3 ligase Cul7, we tested whether Obsl1 or Cul7 could also inhibit HIV-1 production." (PMID 26423533, 2015). "Here, we summarize the clinical features and auxiliary examination results of four patients with 3M syndrome from four Chinese families, and report one novel variant each in CUL7 and OBSL1, expanding the molecular spectrum of the syndrome." (PMID 37719700, 2023). "With the development of gene diagnosis technology, variants in the CUL7, OBSL1, and CCDC8 genes have been identified as responsible for 3M syndrome." (PMID 37719700, 2023). "They noted that, in terms of the clinical and biochemical 3M syndrome phenotype, children with CUL7 mutations were significantly shorter than those with OBSL1 or CCDC8 mutations." (PMID 32235515, 2020). "A majority of disease-causing mutations for human 3M syndrome are located within one of three genes, with approximately 70% of cases occurring within the CUL7 gene, 25% in the OBSL1 gene and 5% within the CCD8 gene." (PMID 32933480, 2020). "Genetically confirmed patients with 3M syndrome carry mutations in CCDC8 (5%), OBSL1 (25%) or CUL7 (70%)." (PMID 32235515, 2020). "The 3M syndrome is caused by loss-of-function mutations in the genes encoding cullin 7 (CUL7), obscurin-like 1 (OBSL1), and coiled-coil domain containing protein 8 (CCDC8)." (PMID 27796265, 2017). "Mutations in CUL7, OBSL1 and CCDC8, leading to disordered ubiquitination, cause one of the commonest primordial growth disorders, 3-M syndrome." (PMID 24711643, 2014). "Our previously published transcriptomic data from 3-M syndrome patients with null mutations in either CUL7, OBSL1 or CCDC8 revealed that IGF2 expression is significantly reduced." (PMID 24711643, 2014). "The diagnosis of 3M syndrome could be confirmed by identifying biallelic variants in CUL7, OBSL1, or CCDC8." (PMID 37877343, 2023). "The prevalence of 3M syndrome has not yet been clearly defined, but pathogenic variants of three genes, namely, CUL7 (3M1, MIM #273750), OBSL1 (3M2, MIM #612921), and CCDC8 (3M3, MIM #614205), were responsible for 77.5%, 16%, and <5% of 3M syndrome cases, respectively." (PMID 37877343, 2023). "The OBSL1 gene was considered as a strong candidate, based on the phenotypic similarity between 3M syndrome-2 in humans and the BCRHS-affected lambs, as well as its biological function as a widespread cytoskeletal adaptor protein important for tissue stabilization in multiple organs." (PMID 32933480, 2020). "While the function of OBSL1 gene is not well characterized, rare mutations in OBSL1 lead to severe pre-natal and postnatal growth restriction known as 3-M syndrome, an autosomal-recessive growth disorder." (PMID 30400783, 2018).
3-M syndrome (continued). "While CUL7 and OBSL1 account for ~94% of known 3-M syndrome cases, the remaining 6% (at least partly accounted for by CCDC8 mutations) of undiagnosed cases suggests that additional genes and perhaps regulatory (non-coding) mutations in known genes are yet to be implicated." (PMID 25923536, 2015). "OMIM 273750 (3-M syndrome) is a rare autosomal recessive condition caused by homozygous or compound heterozygous pathogenic variants in genes encoding cullin 7 (CUL7; type 1: MIM *609577), obscurin-like 1 (OBSL1; type 2: MIM *612921), or coiled-coil domain containing 8 (CCDC8; type 3: MIM *614205)." (PMID 38847008, 2024). "3‐M syndrome is classified into types I, II, and III, which have been identified to be associated with the exclusive variants in cullin 7 (CUL7; MIM *609577), obscurin‐like 1 (OBSL1; MIM *610991), and coiled‐coil domain‐containing protein 8 (CCDC8; MIM *614145) genes, respectively." (PMID 32141654, 2020). "Whole-exome sequencing and genome-wide homozygosity mapping revealed a previously reported frameshift mutation in the OBSL1 gene (c.1273insA p.T425nfsX40), consistent with a diagnosis of 3-M Syndrome 2 (OMIM #612921), which had not been anticipated from the clinical findings." (PMID 25923536, 2015). "In this study, we have used proteomic and transcriptomic approaches to identify the putative interacting partners of CUL7, OBSL1 and CCDC8 to create a 3-M syndrome interactome." (PMID 24711643, 2014). "Exome sequencing revealed that two patients with 3M syndrome had homozygous variants of the CUL7 gene: one novel pathogenic variant and one previously reported pathogenic variant; the other two patients were heterozygous for variants in OBSL1, one of which had not been reported previously." (PMID 37719700, 2023). "Whether there is any connection between OBSL1 recruitment of CUL7 to the Golgi and growth retardation in 3 M Syndrome is not known." (PMID 23029530, 2012).
growth disorder (3 papers, 2015 to 2025). "As Obsl1 is ubiquitously expressed and its mutations lead to a growth disorder in affected patients, we also investigated the phenotype of global Obsl1-knockout mice." (PMID 31098411, 2019). "It is thought that 3M-growth syndrome is caused by a deficiency in protein turnover due to the finding that a majority of patients with 3M-growth disorder display mutations in cullin-7, Obsl1, and Ccdc8." (PMID 31098411, 2019).
hypospadias (1 paper, 2025). Hypospadias is the displacement of the urethral meatus on the ventrum of the penis. "The same family also has the OBSL1 frameshift variant, with previous evidence suggesting that mutations in this gene can be associated with the hypospadias phenotype." (PMID 41300791, 2025).
osteogenesis imperfecta (1 paper, 2022). Osteogenesis imperfecta (OI) comprises a heterogeneous group of genetic disorders characterized by increased bone fragility, low bone mass, and susceptibility to bone fractures with variable severity. "In sheep, frameshift in OBSL1 has been shown to affect brachygnathia inferior, and mutations in COL1A1 and COL1A2 cause osteogenesis imperfecta." (PMID 35008901, 2022).
ovarian carcinoma (1 paper, 2022). A malignant neoplasm originating from the surface ovarian epithelium. "Furthermore, correlation analysis between 182 DEGs and MEX3A was applied using TCGA ovarian cancer data to obtain 7 DEGs (CSNKE1, OBSL1, DNASE1, ZNF711, TIMELESS, SAMD11, and BCL9) that were positively associated with MEX3A expression (Spearman’s correlation≥0.3)." (PMID 35715407, 2022).
Stroke (1 paper, 2023). Sudden impairment of blood flow to a part of the brain due to occlusion or rupture of an artery to the brain. "Investigations of PKP4, DLG1, DLG2, PTPRS and OBSL1 found insufficient evidence to provide a direct link between these genes and neurodegenerative or stroke events." (PMID 37422595, 2023).
cancer (6 papers, 2013 to 2024). A tumor composed of atypical neoplastic, often pleomorphic cells that invade other tissues. "For NCALD and OBSL1, only cancer cells expressed canonical protein-coding isoforms, while other cells expressed short noncoding isoforms." (PMID 38012143, 2023). "Previous work has examined the role of CUL7 and OBSL1 either in mouse studies or using gene overexpression or knockdown strategies in immortalised cancer cell lines." (PMID 24148222, 2013). "However, the specific involvement of OBSL1 in cancer is insufficiently explored." (PMID 33105711, 2020).
tumor (2 papers, 2022 to 2024). "Second post-CIR time point identified cullin 7 (CUL7) and last time point acyl-coa synthetase long chain family member 4 (ACSL4) with NF2, OBSL1 and YWHAE as highly connected components, all being described or hypothesized to play roles in tumor development." (PMID 35158950, 2022).
myopathies (1 paper, 2019). "Accordingly, obscurin mutations have been linked to myopathies, whereas mutations in Obsl1 result in 3M-growth syndrome." (PMID 31098411, 2019).
OBSL1 also shares sentences with these, for which no sentence is quoted: 3M syndrome (19 papers); breast carcinoma (2); infection (2); developmental delay (1); dwarfism (1); intestinal cancer (1); juvenile idiopathic arthritis (1); kidney cancer (1); kidney diseases (1); muscular dystrophies (1); schizophrenia (1); spina bifida (1).